CALCA (calcitonin related polypeptide alpha)
Description:
[Calcitonin]: Calcitonin is a peptide hormone that causes a rapid but short-lived drop in the level of calcium and phosphate in blood by promoting the incorporation of those ions in the bones. Calcitonin function is mediated by the calcitonin receptor/CALCR and the CALCR-RAMP2 (AMYR2) receptor complex. [Katacalcin]: Katacalcin is a potent plasma calcium-lowering peptide. CGRP1/CALCA is a peptide hormone that induces vasodilation mediated by the CALCRL-RAMP1 receptor complex. Dilates a variety of vessels including the coronary, cerebral and systemic vasculature. Its abundance in the CNS also points toward a neurotransmitter or neuromodulator role. It also elevates platelet cAMP. CGRP1 can also bind and activate CALCR-RAMP1 (AMYR1) receptor complex.
Synonyms: CT; CALC1; CGRP1; CGRP-I; CGRP; CGRP-alpha; KC; PCT
Tractability: Small molecule: a structure with a bound ligand is known; it belongs to a druggable protein family. Antibody: its Gene Ontology location is reachable by antibodies, with high confidence; UniProt places it where antibodies can reach, with medium confidence; UniProt predicts a signal peptide or a membrane-spanning region.
Target class: Secreted protein
Gene: Protein-coding gene on chromosome 11 (14,966,622 to 14,972,354, reverse strand). Ensembl gene ENSG00000110680.
Subcellular location: Secreted
Pathways (Reactome):
Signal Transduction: Calcitonin-like ligand receptors; G alpha (s) signalling events
Metabolism of proteins: Amyloid fiber formation
Gene Ontology:
Molecular function: calcitonin receptor binding; hormone activity; identical protein binding; protein binding; receptor ligand activity
Biological process: activation of protein kinase activity; adenylate cyclase-activating G protein-coupled receptor signaling pathway; amylin receptor 2 signaling pathway; calcitonin family receptor signaling pathway; embryo implantation; monocyte chemotaxis; negative regulation of bone resorption; negative regulation of DNA-templated transcription; positive regulation of cytosolic calcium ion concentration; regulation of cytosolic calcium ion concentration; cellular response to nerve growth factor stimulus; cellular response to tumor necrosis factor; negative regulation of blood pressure; negative regulation of smooth muscle contraction; vasodilation
Cellular component: extracellular region; axon; hippocampal mossy fiber to CA3 synapse; neuronal cell body; neuronal dense core vesicle
Genetic constraint (gnomAD): Loss-of-function variants: 4 observed, 7.7 expected, observed/expected ratio (o/e) 0.52, 90% interval 0.25 to 1.19. That is too few expected variants to judge how well the gene tolerates losing a copy. Missense variants: 174 observed, 186.25 expected, observed/expected ratio (o/e) 0.93, 90% interval 0.82 to 1.06. Synonymous variants: 78 observed, 74.39 expected, observed/expected ratio (o/e) 1.05, 90% interval 0.87 to 1.27.
Homologues: Orthologues: chimpanzee CALCA (99% identical), macaque CALCA (94% identical), rabbit CALCA (84% identical), rat Calca (74% identical), dog CRSP-2 (72% identical), dog CRSP-3 (66% identical), mouse Calca (48% identical), dog CRSP-4 (42% identical). Paralogues in human: CALCB (54% identical), IAPP (14% identical).
Diseases named in the same sentence as CALCA in open-access papers:
CALCA is named in the same sentence as 103 diseases in open-access papers, as found by Europe PMC text mining. Sharing a sentence is not in itself a finding about the gene and the disease. The quoted sentences say what the papers report.
migraine (26 papers, 2017 to 2025). "Migraine‐related genes (e.g., CALCA, PRDM16) show a moderate association (OR = 1.85, 95% CI [1.05–3.24]), suggesting a genetic influence on triptan response beyond pain pathways." (PMID 41121943, 2025). "The rs3781719 (T>C) single nucleotide polymorphism of 5-UTR in the promoter region of CALCA gene can also affect the expression of CGRP in the process of migraine." (PMID 35132349, 2022). "The new risk loci include genes encoding recent migraine-specific drug targets, namely calcitonin gene-related peptide (CALCA/CALCB) and serotonin 1F receptor (HTR1F)." (PMID 35115687, 2022). "Moderate associations were observed for migraine susceptibility genes, including CALCA and PRDM16 (pooled OR = 1.8), implying that genetic predisposition may also affect pharmacological efficacy." (PMID 41121943, 2025). "Additionally, epigenetic modifications of calcitonin gene-related peptide alpha (CALCA) have been implicated in migraine susceptibility, further supporting the role of these gasotransmitters in disease pathology." (PMID 40391079, 2025). "The study provided the first evidence that the methylation of CALCA is reduced in patients with migraine, and that methylation may be associated with disease characteristics." (PMID 37298078, 2023). "Aligned with our finding of differential splicing in the 5′ untranslated region of CALCA, a single nucleotide polymorphism (rs3781719) located in the promoter region of CALCA has been associated with the response of patients to the OnabotulinumtoxinA chronic migraine therapy." (PMID 35453627, 2022). "Also interesting was the identification of risk loci, containing genes that encode targets for migraine-specific therapeutics, such as CALCA and CALCB genes encoding for CGRP." (PMID 35910262, 2022). "CGRP receptor inhibitors already showed high efficacy in the treatment of migraine, which is presumably caused via CALCA- or CALCB-mediated vasodilatation in the vicinity of the trigeminal ganglia—the only normal tissue type with physiologically high CALCB expression levels found in our analyses." (PMID 30741933, 2019). "Calcitonin gene-related peptide—CGRP (encoded by the gene CALCA)—is primarily expressed by sensory neurons and known to play a key role in inflammation and neuronal sensitization, particularly during nerve damage as well as in migraine." (PMID 29018326, 2017). "It is particularly interesting that methylation of different CpG sites in the CALCA gene is associated with various clinically relevant migraine characteristics, such as the age of migraine onset and the presence and severity of nausea and vomiting during migraine attacks." (PMID 37298078, 2023). "Calcitonin gene-related peptide alpha (CALCA) and Transient receptor potential cation channel subfamily V member 1 (TRPV1) genes are associated with the pathogenesis of headaches, particularly migraines." (PMID 40002876, 2025). "The CALCA and RAMP1 genes encode calcitonin-gene-related peptide (CGRP), which is an important factor involved in migraine pathogenesis." (PMID 40391079, 2025). "We also found associations between the expression of CALCA, EDN1, IL6, NOS3, VCAM1, and VEGF and measures of cerebrovascular function and migraine-related disability when menstrual phase (i.e., follicular, mid-cycle, or luteal) was accounted for." (PMID 38338971, 2024). "Newly detected loci encoded migraine drug targets, such as CGRP (CALCA/CALCB) and serotonin 1F receptor (HTR1F)." (PMID 37755358, 2023). "Regulation of the expression of the calcitonin related polypeptide alpha (CALCA) gene, encoding an isoform of CGRP and expressed in trigeminal ganglia, arouses a significant interest to improve migraine therapy targeting CGRP and its receptor." (PMID 37326902, 2023). "These included the CALCA and CALCB genes, which encode CGRPs targeted by migraine drugs, and the HTR1F gene, which encodes the 5-HT1F receptor." (PMID 37176049, 2023).
migraine (continued). "Genes that code for current therapeutic targets for migraines, such as calcitonin gene-related peptide (CGRP) (CALCA/CALCB) and serotonin 1F receptor, are among the new risk loci identified for the disease (HTR1F)." (PMID 37474899, 2023). "Modifications of the epigenetic profile of the CALCA gene in migraine include DNA methylation, as the promoter of the gene has two CpG islands with two CpG sites that are hypomethylated in migraine patients." (PMID 37199585, 2023). "Changes in histone modification pattern and effects of micro RNAs (miRNAs), circular RNAs, and long-coding RNAs (lncRNAs) on the CALCA gene were also related to migraine." (PMID 37199585, 2023). "Two of the new risk loci contain genes (CALCA/CALCB and HTR1F) whose protein products are closely related to targets of two migraine-specific drug therapies." (PMID 35115687, 2022). "We also noted that DKK1 and CALCA—which encodes CGRP, a migraine-specific drug target—have a similar pattern of RNA expression across ten HPA brain regions with a high expression in “Pons and Medulla oblongata” that is a part of the brain stem." (PMID 35546551, 2022). "This important study pointed at glial CALCA as an important element in migraine pathophysiology and a potential marker in this disease." (PMID 35682830, 2022). "No overall difference was found in the global methylation of CALCA in patients with migraine and controls." (PMID 30238173, 2018). "Evidence suggests that alterations in the DNA methylation patterns of genes related to migraines, including calcitonin gene-related peptide alpha (CALCA) and receptor activity modifying protein 1 (RAMP1), result in aberrant protein expression, ultimately contributing to migraine." (PMID 40391079, 2025). "We recently provided some arguments that epigenetic regulation of the CALCA gene may be explored to increase efficacy and safety of migraine treatment." (PMID 37326902, 2023). "The promoter of the CALCA gene has two CpG islands that may be specifically methylated in migraine patients." (PMID 35682830, 2022). "The aim of the study was to screen DNA methylation of CALCA gene in patients with migraine." (PMID 30238173, 2018). "Additionally, epigenetic regulation – particularly the involvement of CALCA and RAMP1, which encode CGRP and its receptor – suggests that gasotransmitter interactions may have broader implications for migraine heritability and chronicity." (PMID 40391079, 2025). "The associations between CALCA gene expression and cerebrovascular function are of particular interest as the CALCA gene encodes calcitonin gene-related peptide (CGRP), which is a potent vasodilator and inflammatory mediator that is thought to be involved in migraine pathophysiology." (PMID 38338971, 2024). "Therefore, the researchers concluded that the upregulation of miR-30a may relieve migraine by the degradation of CALCA." (PMID 37432603, 2023). "In contrast, CALCA and PRDM16 polymorphisms showed moderate evidence, and GRIA1 and SCN1A showed weaker evidence to explain nonresponsive migraine patients to Triptan treatment." (PMID 41121943, 2025). "The expressions of CALCA and VEGF were generally associated with increased cerebral blood flow velocity and neurovascular coupling capacity regardless of menstrual phase or migraine status (i.e., hormonal migraineur or control)." (PMID 38338971, 2024). "For example, Calca (calcitonin-related polypeptide alpha, which is involved in migraine) was selectively expressed in C20 of mice, but CALCA almost did not exist in human spinal neurons." (PMID 38289829, 2024). "Global DNA methylation of CALCA gene in migraineurs does not differ from controls, However, DNA methylation status in two CpG islands of the promoter region is lower in patients with migraine." (PMID 30238173, 2018).
migraine (continued). "The neuropeptide CGRP results from cleavage of a calcitonin-related polypeptide alpha (CALCA) isoform, but bioactive neuropeptides resulting from other CALCA isoforms including calcitonin are not known to participate in migraine." (PMID 35453627, 2022).
Sepsis (8 papers, 2013 to 2024). Sepsis is defined as life-threatening organ dysfunction caused by a dysregulated host response to infection. "In recent years, great progress has been made in searching for biomarkers of sepsis, including CALCA (also known as PCT), C-reactive protein, and interleukin-6 which have been found to be biomarkers of sepsis." (PMID 32596378, 2020). "Procalcitonin (CALCA) C-reactive protein, interleukin (IL)-6, and soluble urokinase-type plasminogen activator receptor may serve as sepsis markers." (PMID 32636717, 2020).
medullary thyroid carcinoma (6 papers, 2020 to 2025). "CALCA, a biomarker for medullary thyroid cancer, was hypersecreted in metastatic pancreatic cancer at least 16.5 months pre-diagnosis." (PMID 33004987, 2020). "Both islands are unmethylated in the CALCA-expressing human medullary thyroid carcinoma TT cell line but are hypermethylated in the CALCA non-expressing non-small-cell lung cancer NCI-H460 cell line." (PMID 35682830, 2022).
bacterial sepsis (4 papers, 2013 to 2021). "These preterm patients showed variation in the DNA methylation status of the CALCA promoter in different types of bacterial sepsis, suggesting different regulation of this gene at the epigenetic level according to the type of infection." (PMID 34322502, 2021). "Retrospective research evaluated whether the DNA methylation pattern of CpG sites in the procalcitonin gene [polypeptide related to α calcitonin (CALCA)] could be used as an epigenetic biomarker for bacterial sepsis in premature newborns." (PMID 34322502, 2021). "In addition, the changes of DNA methylation in the calcitonin-related polypeptide alpha gene are observed in preterm infants with bacterial sepsis." (PMID 27661616, 2016).
breast carcinoma (3 papers, 2015 to 2024). "Other genes selected by Rlogreg, namely KISS1, IGF2BP2, CALCA, PLA1A, and FAM171A1, have been reported to be related to breast cancer or other types of cancer." (PMID 32795265, 2020). "However, none of the RAMPs nor CALCA were consistently expressed higher in the samples from breast cancer patients with bone metastases." (PMID 39266299, 2024).
cervical cancer (3 papers, 2012 to 2021). A primary or metastatic malignant neoplasm involving the cervix. "The expression level of CALCA protein is related to the pathological process of cervical cancer, and the methylation of CALCA gene promoter is closely related to the occurrence of cervical cancer." (PMID 34017995, 2021). "In conclusion, the present studies clearly showed that MEG3, MYOD1, CALCA, hTERT, and RASSF1A methylation in plasma can serve as diagnostic and prognostic biomarkers for cervical cancer patients, providing useful information for clinical management." (PMID 29850477, 2018). "Promoter hypermethylation of some other genes like MYOD1, CALCA, hTERT, and RASSF1A can also be detected in serum samples of cervical cancer patients and are related to lymph node metastasis and FIGO stage." (PMID 29850477, 2018).
diabetes (3 papers, 2019 to 2025). "Additionally, diabetes was associated with a significant reduction in the transcripts of vasodilatory neuropeptides, such as VIP and CALCA, suggesting a mechanism for impaired vascular control." (PMID 40667173, 2025).
Headache (3 papers, 2014 to 2025). Cephalgia, or pain sensed in various parts of the head, not confined to the area of distribution of any nerve. "CALCA encodes a peptide that plays a key role in vasodilation and inflammation, two processes central to the development of headaches." (PMID 40002876, 2025). "As a result, we recognized totally 7 possible causing genes (CALCA, TGFBR2, TNF, ESR1, EDNRA, KCNK18, and MTHFR) of headache in the top 10 genes." (PMID 24991551, 2014). "With this being said, the pathogenesis of migraine headaches and PTH do have fundamental differences that may have contributed to a presumed link between CALCA gene and RAMP1 locus in the data presented herein, but not in the study of adult migraineurs." (PMID 35989941, 2022).
COVID-19 (2 papers, 2023 to 2025). A disease caused by infection with severe acute respiratory syndrome coronavirus 2. "The meta-analysis results showed that CALCA had a significant effect size of 3.64 with a very low p-value of 1.33E-15, indicating a strong association with COVID-19." (PMID 40766923, 2025). "Overall, these results suggest that CALCA, TNF, and PLAT are strongly associated with COVID-19, while PPARG has a relatively weaker association." (PMID 40766923, 2025). "Moreover, the literature-based pathway analysis uncovered a set of specific genes, such as CALCA, ACE, SIRT1, TNF, IL6, CCL2, and others, that were found to mediate the association between OA and COVID-19." (PMID 38020136, 2023).
Hypertension (2 papers, 2023 to 2024). The presence of chronic increased pressure in the systemic arterial system. "Taken together, these studies indicate a clinical relevance for the CALCA system in the pathophysiology of sFLT-1-induced hypertension as it occurs in women with PE that imposes a major risk for cardiovascular disease in future and in non-pregnant women with a history of PE." (PMID 37719463, 2023). "CALCA is a potent vasodilator reported to alleviate hypertension and protect from cardiovascular abnormalities in male mice." (PMID 37719463, 2023). "Therefore, like the reported inhibition of hypertension by CALCA in hypertensive male mice, CALCA appears to render protection from sFLT-1-induced vascular dysfunction and facilitates vascular relaxation in PE pregnancy." (PMID 37719463, 2023). "Therefore, data from this study suggest that CALCA inhibits sFLT-1-mediated mitochondrial alterations in maternal vasculature and inhibits sFLT-1-induced hypertension and fetal growth restriction in a mouse model of PE pregnancy." (PMID 37719463, 2023). "In addition, in vivo studies in a mouse model of PE demonstrate that CALCA treatment protects from the development of sFLT-1-induced PE-like symptoms such as hypertension, ATII hypersensitivity, the elevated albumin–creatinine ratio, and fetal growth restriction." (PMID 37719463, 2023).
lung carcinoma (2 papers, 2019 to 2022). "By real-time quantitative methylation-specific polymerase chain reaction (QMSP), it was found that the level of CALCA methylation in patients with lung cancer was significantly higher than that in benign lung lesions." (PMID 35132349, 2022). "The methylation levels of eight genes (CALCA, HOXA9, RASSF1A, CDKN2A, DLEC1, CDH13, PITX2, and WT1) in ctDNA were significantly higher in lung cancer patients than in non-lung cancer patients." (PMID 31752198, 2019).
myelodysplastic syndrome (2 papers, 2017 to 2022). A clonal hematopoietic disorder characterized by dysplasia and ineffective hematopoiesis in one or more of the hematopoietic cell lines. "Frequent methylation of CALCA has been reported in hematological cancers, especially in myelodysplastic syndromes and in acute leukemia, in which it was associated with a higher risk of relapse and poor clinical outcome." (PMID 28881587, 2017). "Methylation of CALCA promoter in bone marrow cells is often observed in patients with myelodysplastic syndrome (MDS) so demethylated drugs can delay the progression of MDS." (PMID 35132349, 2022).
non-small cell lung carcinoma (2 papers, 2017 to 2022). A group of at least three distinct histological types of lung cancer, including non-small cell squamous cell carcinoma, adenocarcinoma, and large cell carcinoma. "CALCA methylation has also been described in several types of solid tumors and it was associated with poor clinical outcome of patients with non-small cell lung cancer." (PMID 28881587, 2017).